IFNA8 (interferon alpha 8)
Description:
Produced by macrophages, IFN-alpha have antiviral activities. Interferon stimulates the production of two enzymes: a protein kinase and an oligoadenylate synthetase.
Synonyms: IFN-alphaB
Tractability: Antibody: a drug acting on it is in phase 2 or 3 trials; its Gene Ontology location is reachable by antibodies, with high confidence; UniProt places it where antibodies can reach, with medium confidence; UniProt predicts a signal peptide or a membrane-spanning region.
Gene: Protein-coding gene on chromosome 9 (21,409,117 to 21,410,185, forward strand). Ensembl gene ENSG00000120242.
Subcellular location: Secreted
Pathways (Reactome):
Immune System: Interferon alpha/beta signaling; Regulation of IFNA/IFNB signaling; TRAF6 mediated IRF7 activation
Disease: Evasion by RSV of host interferon responses; SARS-CoV-2 activates/modulates innate and adaptive immune responses
Hemostasis: Factors involved in megakaryocyte development and platelet production
Gene Ontology:
Molecular function: protein binding; cytokine activity; cytokine receptor binding; type I interferon receptor binding
Biological process: adaptive immune response; B cell activation involved in immune response; cellular response to virus; humoral immune response; natural killer cell activation involved in immune response; response to exogenous dsRNA; T cell activation involved in immune response; type I interferon-mediated signaling pathway; defense response
Cellular component: extracellular region
Genetic constraint (gnomAD): Loss-of-function variants: 1 observed, 0.5 expected, observed/expected ratio (o/e) 1.99. That is too few expected variants to judge how well the gene tolerates losing a copy. Missense variants: 246 observed, 219.39 expected, observed/expected ratio (o/e) 1.12, 90% interval 1.01 to 1.25. Synonymous variants: 91 observed, 85.77 expected, observed/expected ratio (o/e) 1.06, 90% interval 0.89 to 1.26.
Homologues: Orthologues: chimpanzee IFNA8 (98% identical), macaque IFNA8 (90% identical), pig IFN-ALPHA-9 (67% identical), pig IFN-ALPHA-8 (67% identical), pig IFN-ALPHA-15 (66% identical), pig IFNA1 (66% identical), pig IFN-ALPHA-13 (66% identical), pig IFN-ALPHA-4 (65% identical), pig IFN-ALPHA-1 (64% identical), pig IFN-ALPHA-17 (64% identical), mouse Ifna15 (63% identical), mouse Ifna6 (63% identical), and 32 more. Paralogues in human: IFNA16 (82% identical), IFNA2 (82% identical), IFNA5 (82% identical), IFNA21 (81% identical), IFNA4 (81% identical), IFNA14 (81% identical), IFNA6 (81% identical), IFNA10 (80% identical), IFNA17 (80% identical), IFNA13 (78% identical), IFNA7 (78% identical), IFNA1 (77% identical), and 4 more.
Diseases named in the same sentence as IFNA8 in open-access papers:
IFNA8 is named in the same sentence as 13 diseases in open-access papers, as found by Europe PMC text mining. Sharing a sentence is not in itself a finding about the gene and the disease. The quoted sentences say what the papers report.
Acquired Immunodeficiency Syndrome (1 paper, 2024). "Additionally, patients with Acquired Immunodeficiency Syndrome (AIDS; stage C) showed significantly higher expression of IFNA1/13, IFNA8, IFNA14, IFNA16, IFNA17, and IFNA21 mRNA." (PMID 38543729, 2024).
glioma (1 paper, 2023). A benign or malignant brain and spinal cord tumor that arises from glial cells (astrocytes, oligodendrocytes, ependymal cells). "IFNA8 encodes a cytokine responsible for lymphocyte activation in response to infection, and has been shown to play a role in glioma, a cancer of the central nervous system, with mutations in its promoter region affecting patient survival." (PMID 37862349, 2023).
tumor (4 papers, 2016 to 2022). "Macrophages release interferon alpha-8 (IFNA8), and we found that the high-risk group was associated with high expression of CD163, which is a marker of M2-like tumor-associated macrophages (TAMs)." (PMID 34945004, 2021). "In line with this, we found in the TCGA dataset that loss of expression of IFNA13, IFNA21, IFNA6, IFNA8, IFNB1, or IFNW1 was correlated to poor survival, increasing the evidence for the importance of the tumor-stroma microenvironment interaction in gliomagenesis." (PMID 27172220, 2016).
IFNA8 also shares sentences with these, for which no sentence is quoted: HIV-1 infection (3 papers); cancer (2); infection (2); autoimmune disease (1); B-cell lymphoma (1); E. coli infection (1); influenza (1); lupus nephritis (1); thymoma (1); viral infections (1).